POLR2F (RNA polymerase II, I and III subunit F)
Description:
DNA-dependent RNA polymerase catalyzes the transcription of DNA into RNA using the four ribonucleoside triphosphates as substrates. Common component of RNA polymerases I, II, and III which synthesize ribosomal RNA precursors, mRNA precursors and many functional non-coding RNAs, and small RNAs, such as 5S rRNA and tRNAs, respectively. Pol II is the central component of the basal RNA polymerase II transcription machinery. Pols are composed of mobile elements that move relative to each other. In Pol II, POLR2F/RPABC2 is part of the clamp element and together with parts of POLR2A/RPB1 and POLR2B/RPB2 forms a pocket to which the POLR2D/RPB4-POLR2G/RPB7 subcomplex binds.
Synonyms: RPB14.4; POLRF; RPB6; HRBP14.4; RPABC14.4; RPABC2; RPC15
Tractability: Small molecule: a structure with a bound ligand is known. PROTAC: ubiquitination databases record sites on it; its protein half-life has been measured.
Safety:
Unwanted effects reported when the protein is acted on. In parentheses: how it was acted on, where the effect was seen, and who reports it.
neurotoxicity (source: ClinPGx)
Gene: Protein-coding gene on chromosome 22 (37,952,607 to 38,041,915, forward strand). Ensembl gene ENSG00000100142.
Subcellular location: Nucleus; Nucleus, nucleolus
Subcellular location (Human Protein Atlas): Nucleoli fibrillar center; Nucleoplasm
Pathways (Reactome):
Gene expression (Transcription): B-WICH complex positively regulates rRNA expression; Formation of RNA Pol II elongation complex; Formation of the Early Elongation Complex; MicroRNA (miRNA) biogenesis; NoRC negatively regulates rRNA expression; PIWI-interacting RNA (piRNA) biogenesis; RNA Pol II CTD phosphorylation and interaction with CE; RNA Polymerase I Promoter Escape; RNA Polymerase I Transcription Initiation; RNA Polymerase I Transcription Termination; RNA Polymerase II Pre-transcription Events; RNA Polymerase II Promoter Escape; RNA Polymerase II Transcription Elongation; RNA Polymerase II Transcription Initiation; RNA Polymerase II Transcription Initiation And Promoter Clearance; RNA Polymerase II Transcription Pre-Initiation And Promoter Opening; RNA Polymerase III Abortive And Retractive Initiation; RNA Polymerase III Chain Elongation; RNA Polymerase III Transcription Initiation From Type 1 Promoter; RNA Polymerase III Transcription Initiation From Type 2 Promoter; RNA Polymerase III Transcription Initiation From Type 3 Promoter; RNA Polymerase III Transcription Termination; RNA polymerase II transcribes snRNA genes; Transcriptional regulation by small RNAs
Disease: Abortive elongation of HIV-1 transcript in the absence of Tat; Dengue Virus-Host Interactions; Formation of HIV elongation complex in the absence of HIV Tat; Formation of HIV-1 elongation complex containing HIV-1 Tat; Formation of the HIV-1 Early Elongation Complex; HIV Transcription Initiation; HIV elongation arrest and recovery; Pausing and recovery of HIV elongation; Pausing and recovery of Tat-mediated HIV elongation; RNA Pol II CTD phosphorylation and interaction with CE during HIV infection; RNA Polymerase II HIV Promoter Escape; Signaling by FGFR2 IIIa TM; Tat-mediated HIV elongation arrest and recovery; Tat-mediated elongation of the HIV-1 transcript; Transcription of the HIV genome
and 15 more pathways
Gene Ontology:
Molecular function: DNA-directed RNA polymerase activity; DNA binding
Biological process: termination of RNA polymerase III transcription; transcription by RNA polymerase II; transcription by RNA polymerase III; transcription elongation by RNA polymerase I; transcription elongation by RNA polymerase II; transcription initiation at RNA polymerase II promoter; transcription initiation at RNA polymerase III promoter; nucleolar large rRNA transcription by RNA polymerase I; termination of RNA polymerase I transcription; transcription by RNA polymerase I; transcription initiation at RNA polymerase I promoter; tRNA transcription by RNA polymerase III; DNA-templated transcription
Cellular component: fibrillar center; nucleoplasm; nucleus; RNA polymerase I complex; RNA polymerase II, core complex; RNA polymerase III complex; cytosol; nucleolus
Genetic constraint (gnomAD): Loss-of-function variants: 12 observed, 19.68 expected, observed/expected ratio (o/e) 0.61, 90% interval 0.39 to 0.99. The upper end of that interval is the gene's LOEUF score, 0.99, which puts it in group 4 of 6, group 1 being the genes least tolerant of losing a copy. Missense variants: 106 observed, 147.75 expected, observed/expected ratio (o/e) 0.72, 90% interval 0.61 to 0.84. Synonymous variants: 50 observed, 58.07 expected, observed/expected ratio (o/e) 0.86, 90% interval 0.69 to 1.09.
Homologues: Orthologues: guinea pig POLR2F (100% identical), rabbit POLR2F (100% identical), mouse Polr2f (99% identical), pig POLR2F (99% identical), rat Polr2f (99% identical), tropical clawed frog polr2f (94% identical), zebrafish polr2f (87% identical), chimpanzee POLR2F (81% identical), macaque POLR2F (80% identical), Drosophila melanogaster Polr2F (69% identical), Caenorhabditis elegans rpb-6 (62% identical).
Diseases named in the same sentence as POLR2F in open-access papers:
POLR2F is named in the same sentence as 25 diseases in open-access papers, as found by Europe PMC text mining. Sharing a sentence is not in itself a finding about the gene and the disease. The quoted sentences say what the papers report.
glioma (4 papers, 2022 to 2025). A benign or malignant brain and spinal cord tumor that arises from glial cells (astrocytes, oligodendrocytes, ependymal cells). "In our selection of seven HRD-related genes, the high expression of PLK3, PRMT6, UNG, and FANCB is associated with poorer prognosis in glioma patients, whereas the high expression of POLR2F, INO80D, and PTEN is linked to better prognosis." (PMID 41417782, 2025). "In literature, only BRCA1, TRIM21, and POLR2F have been implicated in the progression of glioma." (PMID 36118697, 2022). "Lin established a 6-RBP gene signature consisting of POLR2F, DYNC1H1, SMAD9, TRIM21, BRCA1, and ERI1 in another bioinformatics work, allowing for a complete assessment of glioma and ischemic stroke." (PMID 37884559, 2023). "First, six prognostic-related RBP genes (POLR2F, DYNC1H1, SMAD9, TRIM21, BRCA1, and ERI1) were obtained from the TCGA-glioma dataset." (PMID 36118697, 2022). "The volcanic plot showed the differential analysis results of these six RBP genes, which showed that POLR2F and DYNC1H1 were downregulated in glioma, while TRIM21, BRCA1, ERI1, and SMAD9 were upregulated in glioma." (PMID 36118697, 2022). "In all WHO grade II-IV gliomas, DNAss was positively correlated with the RBPS score, ERI1, BRCA1, and TRIM21, while negatively correlated with POLR2F, DYNC1H1, and SMAD9 [Spearman correlation, Benjamini-Hochberg (BH)-adjusted p < 0.05]." (PMID 36118697, 2022). "Among them, POLR2F, DYNC1H1, and SMAD9 in tumor tissues of patients with glioma were downregulated as compared to normal tissues adjacent to cancer, while TRIM21, BRCA1, and ERI1 were upregulated." (PMID 36118697, 2022).
colorectal cancer (2 papers, 2011 to 2019). A primary or metastatic malignant neoplasm that affects the colon or rectum. "POLR2F is significantly high expression in colorectal carcinomas and potential molecule in carcinogenesis." (PMID 31576243, 2019).
dementia (2 papers, 2022 to 2023). Loss of intellectual abilities interfering with an individual's social and occupational functions. "Upregulation of SMAD9 was associated with dementia, while downregulation of POLR2F was associated with aging-related hypoxic stress." (PMID 36118697, 2022). "In this RBPS, SMAD9 was found to be associated with dementia; POLR2F and ERI1 were identified to be associated with aging." (PMID 36118697, 2022). "A study reported that stroke was associated with cognitive impairment and dementia in older adults, and the six RNA-binding protein (RBP) genes (POLR2F, DYNC1H1, SMAD9, TRIM21, BRCA1, and ERI1) might participate in the process by mediating the hypoxic responses and angiogenesis." (PMID 37006557, 2023).
ischemic stroke (2 papers, 2022 to 2023). A stroke disorder caused by obstruction of blood flow to the brain, due to thrombotic (local blood clot formation) or embolic (due to a blood clot or other material traveling from another site) event. "Genome-wide association analysis shows that POLR2F (22q13.1) is associated with periventricular white matter hyperintensions (PVWMH), and PVWMH are associated with ischemic stroke." (PMID 36118697, 2022). "Differentially expressed analysis showed that POLR2F, BRCA1, and TRIM21 in this RBPS were associated with ischemic stroke." (PMID 36118697, 2022).
cervical cancer (1 paper, 2020). A primary or metastatic malignant neoplasm involving the cervix. "TP53BP1, MCM9 (at higher than mean levels), POLR2F and SIRT6 (at lower than mean levels), were associated with an increase in patients experiencing cervical cancer recurrence/progression following postoperative radiation therapy when HPV18 positive, but not HPV16 positive." (PMID 32066835, 2020). "Moreover, increased expression levels of TP53BP1 and MCM9 and decreased expression levels of POLR2F and SIRT6 were found to be specifically associated with a poorer prognosis for HPV18+ (but not HPV16+) cervical cancer patients following PRT." (PMID 32066835, 2020).
gastric tumors (1 paper, 2023). "Drug (TAS-106) targeting POLR2F has been found to inhibit the growth of colorectal and gastric tumors in mice." (PMID 37726845, 2023).
hypercoagulation (1 paper, 2022). "The upregulation of TRIM21 and BRCA1 and the downregulation of POLR2F were related to platelet activation and increased coagulation, thus suggesting that an imbalance among these genes may result in a state of hypercoagulation, which could easily lead to an ischemic cerebral infarction." (PMID 36118697, 2022).
hypertensive renal disease (1 paper, 2026). "POLR2F, TNFRSF10B, and IGFBP2 were positively associated with all five diseases, with Mendelian randomization supporting genetic associations of POLR2F with CHD and IGFBP2 with hypertensive renal disease." (PMID 41559658, 2026).
hypothyroidism (1 paper, 2025). Abnormally low levels of thyroid hormone. "For example, genetically predicted plasma levels of ALDH2, BCL2L15, WASL, POLR2F, and ADPGK were positively associated with hypothyroidism risk, while H2BC21 and H2BC26 showed negative associations." (PMID 40868097, 2025).
maturity onset diabetes (1 paper, 2023). "POLR2F was involved in olfactory transduction, drug metabolism other enzymes, glycosphingolipid biosynthesis lacto and neolacto series, and maturity onset diabetes of the young." (PMID 37884559, 2023).
neuroblastoma (1 paper, 2021). Neuroblastoma (NB) is the most common solid, extracranial childhood tumor. "Previous studies with qPCR have found HPRT1 and SDHA to show low expression variability in primary neuroblastoma and also, specifically for the SY5Y line, GAPDH, M-RIP, and POLR2F were found to be reliable genes to be used as normalization factors." (PMID 34066513, 2021).
cancer (7 papers, 2007 to 2025). A tumor composed of atypical neoplastic, often pleomorphic cells that invade other tissues. "On the other hand, the hub gene Polr2f is often found in cancer cells." (PMID 33919822, 2021). "The findings of Antonacopoulou's study shed light on the higher expression of POLR2F and PRNP in carcinomas compared to normal tissue samples, indicating a possible role in colorectal cancer." (PMID 37884559, 2023). "Genes labeled by IPA as being cancer related (COL18A1, STAT5B, CTDSPL) were also involved with infection as were genes involved in apoptosis and growth (CTDSPL, POLR2F, ZBTB16)." (PMID 18047719, 2007).
tumor (3 papers, 2022 to 2023). "From the perspective of biological function, the increased expression of POLR2F may reflect the high transcriptional activity in tumor cells." (PMID 35681277, 2023).
cardiovascular diseases (1 paper, 2025). "In another aspect, genetic susceptibility to higher levels of ALDH2, POLR2F, and ADPGK were associated with increased risks of various cardiovascular diseases." (PMID 40868097, 2025).
POLR2F also shares sentences with these, for which no sentence is quoted: colon cancer (2 papers); autoimmune disease (1); Cognitive impairment (1); Huntington disease (1); infection (1); lung carcinoma (1); melanoma (1); rectal cancer (1); Stroke (1); thyroid cancer (1); virus infection (1).